SIRT1 (sirtuin 1)
Diseases named in the same sentence as SIRT1 in open-access papers (continued):
Sharing a sentence is not in itself a finding about the gene and the disease.
diabetes (continued). "In diabetes, due to hypermethylation of promoter DNA, Sirtuin 1 (Sirt1), a NAD-dependent deacetylase, is also inhibited." (PMID 31277234, 2019). "A reduction in the NAD+/NADH ratio in the presence of excess nutrient supply results in lower renal expression of sirtuin-1 in diabetic patients and experimental models of diabetes." (PMID 30707256, 2019). "Diabetes caused high TGF-β1 expression in the kidney and albuminuria was blunted in sirtuin-1 overexpressing transgenic mice." (PMID 30707256, 2019). "For example, the well-known SIRT1 activator, resveratrol is a natural compound with potential therapeutic use in the treatment of many diseases, including cancer, diabetes, and other metabolic disorders." (PMID 31598701, 2019). "Inhibition of oxidative stress with melatonin attenuates ischemia AKI in diabetes by improving the SIRT1/Nrf2/HO-1 signaling." (PMID 30578379, 2019). "This explains the observed phenomena of reduced expression of SIRT1 and increased expression of p66Shc in endothelial cells due to diabetes." (PMID 30918103, 2019). "Our study demonstrates the partial reversal of resveratrol’s beneficial effects in a model of concurrent diabetes and AD in rats by coadministration of resveratrol with a Sirt1 inhibitor." (PMID 32038127, 2019). "Diabetes-induced downregulation of sirtuin-1 increases OS in mitochondria by promoting histone H3 and p66Shc acetylation." (PMID 30707256, 2019). "Diabetes-induced downregulation of sirtuin-1 leads to activation of NF-κB signaling, which promotes the activation of downstream pro-inflammatory factors and inhibits anti-oxidative stress Nrf2/ARE pathway involved in the development of DN." (PMID 30707256, 2019). "An 80% reduction in SIRT1 levels was observed in patients with diabetes, both in serum and the arterial smooth muscle layer, whilst both RUNX2 and Osteocalcin levels were elevated." (PMID 30696833, 2019). "Although we have previously demonstrated that proximal SIRT1 protected against reactive oxygen species-mediated kidney injury, we recently uncovered that SIRT1 was specifically protective against hyperglycemia and diabetes-induced kidney damage." (PMID 30859351, 2019). "Some clinical studies for SIRT1 activators have already been initiated for diseases including cardiovascular disease, human cancers, diabetes, and Alzheimer disease." (PMID 31287252, 2019). "Affecting the SIRT1 and fetuin-A levels introduces a new known mechanism of probiotic action in diabetes management." (PMID 29803203, 2019). "In an animal models of type 1 diabetes mellitus induced by streptozotocin, decreased myocardial Sirt1 activity leading to decreased Akt phosphorylation and increased Drp1 activity increases myocardial susceptibility to IR injury." (PMID 31151453, 2019). "We found that diabetes reduced SIRT1 at both time points, but that glycyrrhizin significantly increased levels at 2 and 6 months." (PMID 31159195, 2019). "According to our findings, we suggest that melatonin protects diabetes kidney by activating SIRT1/Nrf2/HO-1 pathway." (PMID 30578379, 2019). "Functional defects in SIRT1 lead to premature cardiovascular and cerebrovascular diseases, metabolic disorders, diabetes, and neurodegenerative diseases." (PMID 31182679, 2019). "Melatonin attenuates apoptosis and oxidative stress in diabetes ischemia AKI through activation of the SIRT1/Nrf2/HO-1 pathway." (PMID 30578379, 2019). "SIRT1 regulates metabolism and inflammation in various tissues which can be the key regulator of exercise-mediated protection against diabetes at tissue level." (PMID 30988688, 2019).
diabetes (continued). "Resveratrol prevents neurodegeneration in a rat model of diabetes with concurrent AD by activating Sirt1 and its downstream targets to regulate the cholinergic system and control oxidative stress and the inflammatory response." (PMID 32038127, 2019). "Recent studies have revealed the decrease of SIRT1 in diabetes patients and the increase of miR-29b-3p in diabetes." (PMID 32063865, 2019). "Firstly, this study clearly demonstrates a significant suppression of SIRT1 in serum from diabetic patients compared to healthy controls, potentially accounting for the prevalence of vascular calcification in patients with diabetes." (PMID 30696833, 2019). "Exercise-induced upregulation of SIRT1 attenuates inflammation and metabolic dysfunction, thereby alleviating the progression of diabetic nephropathy and hepatic steatosis in type 2 diabetes mellitus." (PMID 30988688, 2019). "As shown in 7G and 7H, PHL significantly increased the expression of SIRT1 in diabetes mice compared with CTRL or T1DM groups." (PMID 31076562, 2019). "PRR shRNA reversed the diabetes-induced decrease of pAMPK/tAMPK and SIRT-1 protein expression, and the levels were similar to that of PRR shRNA treated non-diabetic animals." (PMID 31800607, 2019). "It has been reported that the activation of Sirt1 protects against vascular dysfunction in mice with diabetes." (PMID 31118974, 2019). "SIRT1 is also capable of regulating TGF-β1 and ET-1 expressions by p300, while SIRT1 overexpression can prevent diabetes-induced FN upregulation." (PMID 29670886, 2018). "Rizk and colleagues have also shown similar findings where elevating SIRT1 levels, with the administration of L-arginine, significantly prevented diabetes-induced myocardial fibrosis in male Wistar rats." (PMID 29670886, 2018). "Previous studies that explored SIRT1 in diabetes have focussed on type 2 diabetes, showing that SIRT1 activation enhances ß-cell function, improves insulin sensitivity and increases ß cell mass to attenuate hyperglycaemia." (PMID 30228292, 2018). "SIRT1 expression and activity were significantly reduced in experimental models of diabetes mellitus." (PMID 29743980, 2018). "Because SIRT1 has critical effects in chronic inflammatory diseases, including cardiovascular disease and diabetes mellitus, considerable effort has been devoted to discovering pharmaceutical activators of SIRT1 for use in therapeutic applications." (PMID 29572511, 2018). "In conclusion, SGLT2 expression was increased in the kidneys of db/db mice and humans with diabetes, whereas SIRT1 expression was decreased." (PMID 29717156, 2018). "Resveratrol activates the Sirtuin 1 (SIRT1) pathways, according to some recent studies on how resveratrol works in diabetes." (PMID 29743980, 2018). "Identification of SIRT1 activators for diabetes has gained wide attention, such as metformin, resveratrol, and resveratrol derivatives." (PMID 30559718, 2018). "The interdiction of SIRT1 activation can affect the development of age- and obesity-related diseases, such as diabetes, angiocardiopathy and neurodegenerative diseases." (PMID 30110438, 2018). "While abundant data point to the essential role of SIRTs activities, there are genetic polymorphisms of SIRT1 and SIRT2 concerning diabetes." (PMID 30559718, 2018). "RES is a SIRT1 activator that can mitigate type-1 diabetes mellitus-induced sperm abnormalities and DNA damage by activating SIRT1." (PMID 29890735, 2018). "SIRT1 expression is also reduced in obese humans, and meanwhile diabetes is alleviated in SIRT1-overexpressed mice." (PMID 30559718, 2018).
diabetes (continued). "To elucidate a more detailed mechanism for the relationship between SGLT2 and SIRT1, we used obese-type db/db mice with diabetes treated with the SGLT2 inhibitor canagliflozin (Cana) and investigated SIRT1 and SGLT2 expressions." (PMID 29717156, 2018). "In an animal model of diabetes, the SIRT1 is expressed in pancreatic β-cells to enhance insulin secretion in response to glucose." (PMID 30246793, 2018). "Numerous findings have regarded SIRT1 as a promising molecular target in abating MI/R injury in diabetes for its positive roles of regulating oxidative stress and apoptosis." (PMID 29675132, 2018). "SIRT1 expression decreased in db/db mice with diabetes compared with that in db/m mice, which was rescued by Cana treatment in mice with diabetes." (PMID 29717156, 2018). "They found that MSC-CM protected endothelium against diabetes-induced dysfunction by activating the PI3K/Akt/Sirt1/AMPK/PGC-1α cascade, which improved endothelial mitochondrial bioenergetics." (PMID 29152123, 2017). "Pleiotropic activity of SIRT1 makes it an important marker of cellular senescence as well as some diseases such as cardiovascular and neurodegenerative diseases, diabetes or cancer." (PMID 28258519, 2017). "This is endorsed by the finding that metformin acts through hepatic SIRT1 activation as part of its diabetes ameliorating effects; results similarly observed with resveratrol." (PMID 29264533, 2017). "Previous studies have shown that the AMPK/Sirt1/PGC-1α pathway plays an important role in the induction of ROS-induced apoptosis in diabetes." (PMID 29213353, 2017). "This in vivo data demonstrates that the diabetes-induced suppression of AMPK/SIRT1/PGC-1α signaling is activated by GA." (PMID 29238727, 2017). "Herein, the treatment with systemic EOCs or their CM invoked protection of retinal tissue from diabetes insult due to its high antioxidant property, thus leading to reestablishment of SIRT1 activity." (PMID 26836609, 2016). "In animal models of diabetes, SIRT1 activation increases energy expenditure and improves insulin sensitivity." (PMID 26904696, 2016). "Sirtuin 1 (SIRT1) is a nicotinamide adenine dinucleotide-dependent deacetylase, and its dysregulation can lead to ageing, diabetes, and cancer." (PMID 26805727, 2016). "The administration of resveratrol prevents the alteration in SIRT-1 in type-2 diabetes mellitus and SIRT-1, 2, 3 and SIRT-5 in the type 1 diabetes mellitus rat heart." (PMID 27690014, 2016). "Taken together, in this content, we established in vivo rat model of diabetes and in vitro high glucose incubated renal tubular cell and investigated the Sirt1/NF-κB/miR-29/Keap1/Nrf2 signal pathway in process of high glucose induced renal tubular injury." (PMID 26552447, 2015). "These and other studies are proposing the use of Sirt1 activating drugs, such as the red wine component resveratrol, for healthy ageing and control of diabetes." (PMID 26046931, 2015). "This study revealed a collection of novel mechanistic insights on the complex role of Sirt1 in pancreatic islets, which is important to advance therapeutic approaches in diabetes." (PMID 26046931, 2015). "SIRT1 exerts beneficial effects on glucose-lipid homeostasis and insulin sensitivity in diabetes from both animal studies and clinical research." (PMID 26489513, 2015).
diabetes (continued). "In the kidneys and retinas of SIRT1 overexpressing transgenic mice we have further established the existence of such regulation in a STZ-induced type 1 model of diabetes." (PMID 25753689, 2015). "Overexpression of SIRT1 reduces diabetes-exacerbated MI/R injury and oxidative stress via modulating eNOS acitivity in diabetic rats." (PMID 26489513, 2015). "Previous study points out that high glucose reduced Sirt1 expression that mediated protection against renal injury in diabetes." (PMID 26552447, 2015). "This study shows that it is possible to target either SIRT1 or p300 to prevent diabetes-induced alterations." (PMID 25753689, 2015). "Levels of Nampt and Sirt1 were observed to be higher in gastric cancer with diabetes than gastric cancer tissues." (PMID 25815791, 2015). "This study showed a novel SIRT1 mediated protection against renal and retinal injury in diabetes, regulated through p300, ET-1 and TGF-β1." (PMID 25753689, 2015). "SIRT1 has been found to play crucial role in cellular oxidative stress response, metabolism, differentiation, longevity and various diseases including diabetes 20–23." (PMID 25753689, 2015). "Overexpression of SIRT1 reduces diabetes-exacerbated MI/R injury and oxidative stress via activating eNOS in diabetic rats." (PMID 26489513, 2015). "We further expanded the study using SIRT1 overexpressing transgenic mice in which we induced diabetes with streptozotocin (STZ) and examined their renal and retinal tissues." (PMID 25753689, 2015). "SIRT1 activators will exert their activity protecting individuals from diabetes, while inhibition of SIRT2 would protect dopaminergic cell against death both in vitro and in a drosophila model of PD." (PMID 24465703, 2014). "Serum sirtuins (SIRT1, 2 and 3) were significantly lower in frails as compared to nonfrail after adjustment for multiple confounders such as age, gender, diabetes mellitus, hypertension, cognitive impairment, and number of comorbidities." (PMID 25100619, 2014). "SIRT1 plays an important role in a number of human physiological and pathological processes, including chronic inflammation, cancer, diabetes, and longevity, especially in ischemic injury." (PMID 25114706, 2014). "SIRT1 has been reported to play a central role in the regulation of chronic pathogenesis, such as diabetes, neurodegenerative, and chronic inflammatory diseases." (PMID 24624081, 2014). "Recent results have suggested that SIRT1 in proximal tubules protects against albuminuria in diabetes by maintaining nicotinamide mononucleotide concentrations around glomeruli, thus influencing podocyte function." (PMID 24923264, 2014). "Numerous studies have shown that SIRT1 activity is essential in cancer, neurodegenerative diseases, diabetes, cardiovascular disease, and other age-related diseases." (PMID 25386563, 2014). "During the past decade, investigators have reported that SIRT1 activity is essential in cancer, neurodegenerative diseases, diabetes, cardiovascular disease, and other age-related diseases." (PMID 25386563, 2014). "It is shown to attenuate cardiomyocyte apoptosis in heart failure and improve cardiac function in diabetes through SIRT1-dependent way." (PMID 24889822, 2014). "SIRT1 is central to the lifespan and vascular health, but undergoes degradation that contributes to several medical conditions, including diabetes." (PMID 25541949, 2014). "Strategies to target the Nampt-Sirt1-Rev-erb alpha in pancreatic alpha-cells can be useful for the treatment of hyperglucagonemia present in diabetes." (PMID 23936124, 2013). "Retinal SIRT1 mRNA expressions were reduced in both models following 2 months of diabetes and the effects were pronounced after 4 months." (PMID 23342163, 2013).
diabetes (continued). "Generally speaking, alterations of SIRT1 gene expression are associated with changes in cell metabolism, differentiation, proliferation and many other fundamental cell features and may therefore affect numerous diseases such as diabetes, cancer or arteriosclerosis." (PMID 23870485, 2013). "Previous diabetes induction in vivo and high glucose concentrations in vitro significantly downregulated SIRT1 amounts as detected in Western blot assays, whereas TNF-α (30 ng/ml) stimulation failed to induce significant changes." (PMID 23734259, 2013). "How hyperglycemia and diabetes diminish the SIRT1-AMPK axis in atherosclerosis warrants further investigation." (PMID 23825667, 2013). "For example, suppression of SIRT1 has been shown to increase Mφ infiltration into inflamed tissues in mouse models of diabetes and colitis, perhaps by increased NFkB activity and increased expression of MMP9." (PMID 24386389, 2013). "Use of cell models as well as tissue-specific SIRT1 knockout mice has uncovered potential roles for SIRT1 in disease settings such as diabetes and cardiovascular disease, inflammation, neurodegeneration and cancer." (PMID 23734259, 2013). "Several chemical compounds are known to affect the SIRT1 activities, and SIRT1 stimulators are currently extensively investigated for the treatment of diabetes." (PMID 22357324, 2012). "Another class of drugs gaining wide acceptance in the treatment of diabetes are sirtuin 1 (SIRT1) activators." (PMID 22203837, 2012). "Mitochondrial dysfunction plays a pivotal role in the development of insulin resistance and diabetes, and Sirt1 activation has been suggested as a therapeutic target." (PMID 22822451, 2012). "Mice models mildly overexpressing SIRT1 demonstrated ameliorated glucose tolerance when insulin resistance and/or diabetes were induced." (PMID 23137106, 2012). "SIRT1 blocks endothelial cell apoptosis during experimental diabetes, and prevents age-related cardiac hypertrophy, apoptosis, cardiac dysfunction, and senescence marker expression in mice." (PMID 22545721, 2012). "Variants of the SIRT1, SIRT2, SIRT6, UCP1, UCP2, and UCP3 genes have been related to diabetes, obesity, serum high-density lipoprotein cholesterol (HDL), and inflammation." (PMID 22087257, 2011). "Specifically, low-frequency EA improved insulin sensitivity in a mouse model of genetic insulin resistance and diabetes, at least in part, via stimulation of SIRT1/PGC-1α in the skeletal muscle." (PMID 20981161, 2011). "H3K56 is acetylated by CBP and p300, and deacetylated by SIRT1, all are proteins with important roles in diabetes and insulin signaling." (PMID 21655096, 2011). "Together, our data provide evidence that alteration of Foxo4 acetylation and down regulation of Sirt1 expression in diabetes promote podocyte apoptosis." (PMID 21858169, 2011). "Treatment of obese mice with resveratrol, a pharmacological activator of SIRT1, modestly but significantly improved longevity and, perhaps more importantly, offered some protection against the development of type 2 diabetes mellitus and metabolic syndrome." (PMID 19107194, 2008). "It is regulated by phosphorylation, ubiquitination, and acetylation; the latter is modulated by SIRT1, which deacetylates p65 to inhibit its activity and control the exacerbation of inflammation, offering a therapeutic avenue in diseases such as diabetes, atherosclerosis, and cancer." (PMID 41141596, 2025). "In addition, SIRT1 has also been shown to attenuate diabetic nephropathy in vitro and in vivo experimental models of diabetes involving podocytes, mesangial cells, and renal proximal tubular cells." (PMID 40649025, 2025). "Second, systematic detection limitations: Oxidative stress and systemic inflammation, both common in diabetes, may inhibit SIRT1 secretion or promote its degradation despite increased mRNA." (PMID 40903907, 2025).